ISG15 (ISG15 ubiquitin like modifier)
Diseases named in the same sentence as ISG15 in open-access papers (continued):
Sharing a sentence is not in itself a finding about the gene and the disease.
infection (continued). "The persistent ISG expression observed in human ISG15-deficient cells imparts a resistance to infection with multiple families of viruses with both RNA and DNA genomes." (PMID 27193971, 2016). "Accordingly, a reduced viral load in knockout mice on day 8 post-infection was linked to elevated Isg15 and Mx1 transcript in the lungs." (PMID 26709698, 2015). "ISG15 knock-out mice are more susceptible to infection by several viruses, pointing out the relevance of this molecule in the antiviral response in animal models." (PMID 24137104, 2013). "The PKR/MAVS association took place at 4 hrs post-infection in the control cells but was observed 2 hrs earlier in the ISG15-depleted cells." (PMID 22022264, 2011). "The cause of mortality of ISG15 KO mice after infection with VVΔE3L or VVE3LΔ26C was a massive inflammation of lungs with alveolar wall thickening and infiltration of cells." (PMID 18604270, 2008). "In addition, the expression of the il1b and isg15 transcripts also increased in Samhd1-deficient larvae following infection." (PMID 40352920, 2025). "Consequently, ISG15-deficient mice exhibit a divergent phenotype, rendering them more susceptible to infection by various types of viruses." (PMID 38400136, 2024). "However, as we observed a more pronounced DC activation in ΔrfaE-infected cells, we reasoned that this would likely be caused by the proteins that were more abundant after infection with the H. pylori mutant, which included ISG15, MX1and MX2." (PMID 39288239, 2024). "Similarly, complementation with ISG15ΔGG in the ISG15-deficient patient cells also significantly increased infection in IFN-primed cells, while complementation with RFP did not change the number of HIV-1 infected cells." (PMID 35333911, 2022). "Complementation with both wild-type (WT) ISG15 and ISG15ΔGG (incapable of ISGylation while retaining negative regulation activity) was sufficient to reverse this phenotype, restoring susceptibility to infection to levels comparable to WT cells." (PMID 35333911, 2022). "Nevertheless, if ISG15-deficient cells were treated for longer periods with IFN-α prior to infection, they did become resistant, even when IFIT1 was knocked down, suggesting that at later times, the inhibition of protein synthesis was the principal cause of resistance." (PMID 32423918, 2020). "Similarly, mice deficient in UbE1l—the E1 enzyme of ISG15—were also more susceptible to lethal infection by SINV." (PMID 30428561, 2018). "Mice deficient in ISG15 are susceptible to infection with Influenza, Sindbis, and Herpes viruses." (PMID 26259872, 2015). "Furthermore, primary fibroblasts that lack ISG15 or UBE1L are more susceptible to infection and animals deficient in ISG15 have a higher bacterial burden both in the liver and spleen." (PMID 26259872, 2015). "Human patients with inherited ISG15 deficiency develop type I interferonopathy, yet serological tests reveal an enhanced and prolonged resistance to a diverse range of DNA and RNA viruses, accompanied by a reduction in severity, viral replication, and susceptibility to infection." (PMID 38400136, 2024). "“Bystander” cluster F3 fibroblasts also exhibited increased expression of pro-inflammatory genes, including C1QBP and ISG15, suggesting that cocultured fibroblasts may respond to infection-associated induction of pro-inflammatory signaling by host endocervical epithelial cells." (PMID 37874141, 2023). "Indeed, the computed top DEG, typifying each cluster on day 3 in the effector phase of infection, hosted several interferon-induced anti-viral genes (Irf1, Irf7, Ifrd1, Socs1, Socs3, Ifit1, Bst2, and Isg15) as well as genes associated with mature resident Trm cells (Cd69, Nfkbid, Brd2, FosB)." (PMID 35260804, 2022).
infection (continued). "ISG15 has been shown to modify several important molecules linked to and affecting type I interferon signal transduction, is released from cells to mediate extracellular cytokine-like activities, and evidence suggests that IFNβ and ISG15 are induced in parallel as a primary response to infection." (PMID 18851747, 2008). "In normal human bronchial epithelial cells (NHBE), the Sendai virus triggered a rapid and robust expression of multiple antiviral genes with a peak at 6 h post-infection (hpi) with the fold of increase ranging from ~15,000 (for ISG15) to 800,000 (for IFNB1)." (PMID 40298378, 2025). "Here, we show that infection with Chlamydia trachomatis (Ct) induces the expression and secretion of ISG15 in human primary cells and mouse female genital tract (FGT) organoids." (PMID 40627782, 2025). "LFBK cells stimulated with transfected poly(dA:dT) (10 μg/mL) to detect IFN-β, IFN-α, IRF7, IRF3, PKR, MX1, ISG56, and ISG15 at 2, 24, and 48 h infection times using qRT-PCR was investigated." (PMID 40500801, 2025). "PRV induces ISG15 expression and ISGylation (ISG15 modification) in the early stages of infection but is subsequently inhibited by the virus, with gE playing a crucial role in reducing ISG15 expression." (PMID 40285022, 2025). "Significant release of ISG15 was observed only in Ct-infected organoids and not in uninfected controls in both disrupted and intact organoids, demonstrating that mFGT organoids express and secrete ISG15 in response to Ct infection." (PMID 40627782, 2025). "Given that LD accumulation is required for interferon response in the early infection of virus, we measured two ISGs, ISG15 and MX1, which can be induced by type I interferon and possess antiviral capacities." (PMID 39891192, 2025). "Infection of these mFGT organoids with Ct for 3 and 5 days induced high ISG15 expression, demonstrating the production of ISG15 in mFGT tissue." (PMID 40627782, 2025). "Although IFN-γ is not the sole contributor to bacterial clearance, our findings support a critical role for ISG15 in initiating early IFN-γ responses that shape the course of infection." (PMID 40627782, 2025). "ISG15 secretion was investigated in this infection model in intact organoids and in organoids that were disrupted by up-and-down pipetting prior to harvesting the supernatant for ELISA." (PMID 40627782, 2025). "In contrast to the IFN-γ response, IL-10 levels were comparable in WT and ISG15−/− mice at early infection time points (3 dpi)." (PMID 40627782, 2025). "To this end, we examined the polarization characteristics of macrophages during Ct infection under stimulation with IFN-γ or IFN-γ/ISG15." (PMID 40627782, 2025). "ISG15 conjugation strongly attenuates influenza A virus replication early in infection in human cells." (PMID 40103488, 2025). "Compound 10 treatment elevated the expression of cellular antiviral genes, including Ifnb1, Isg15, Isg56, and Mx1, at 4 days post-infection (dpi)." (PMID 40298378, 2025). "We found that ISG15 not only increases during infection but is also secreted by cells in the female genital tract." (PMID 40627782, 2025). "Consistently, we observed that Sec10 knockdown enhanced the mRNA level of Ifn-β, Isg15, Isg54, and Isg56 upon stimulation with poly(dA:dT) or infection with HSV-1." (PMID 40920886, 2025). "While our in vitro findings provide strong support for a modulatory role of ISG15 in macrophages, further in vivo investigation is needed to clarify the relevance of this effect during infection." (PMID 40627782, 2025). "Epithelial cells produce IL-18 in response to Ct infection and we observed elevated IL-18 levels in supernatants of infected mFGT organoids from WT and ISG15−/− mice." (PMID 40627782, 2025). "As expected, ISG15 was upregulated by MVA infection in DF-1 cells, whereas its expression rate was comparable in mock-infected vs. infected DSK cells." (PMID 40981440, 2025).
infection (continued). "We further analyzed the expression of ISG15, a gene encoding for a ubiquitin-like molecule that is highly induced by type I IFN during infection by viral and bacterial pathogens." (PMID 40981440, 2025). "A subtly reduced Mx1 and ISG15 induction was seen after infection with BAD-ΔUS2,3,6,11 and BAD-ΔUS2,3,6." (PMID 40143353, 2025). "The rationale is that immediately after infection, a significant portion of newly made proteins are of viral origins, and the spatial localization of the ISG15 machinery at sites of protein translation would guarantee ISGylation of these viral effectors." (PMID 40631552, 2025). "We believe that this synergistic role of ISG15 is important in the early stages of host infection, particularly in situations where networks of different immune cells are not yet well-established in the infected tissue, or immune cells are not fully activated." (PMID 40627782, 2025). "Isg15 and Ifit1/Isg56 (interferon-induced protein with tetratricopeptide repeats 1) mRNA expression were detected 12 h post infection with levels of Isg15 and Ifit1/Isg56 mRNA 5-fold greater in ΔWD MEFs compared to WT controls." (PMID 40143422, 2025). "It has been shown that in ISG15-deficient THP-1 cells, the infection of HIV-1 was enhanced in both undifferentiated and phorbol-12-myristate-13-acetate (PMA)-differentiated ISG15-deficient THP-1 cells compared with the control." (PMID 40981440, 2025). "Ct infection markedly elevated ISG15 levels in genital tract tissues, especially during the early stages of infection." (PMID 40627782, 2025). "Five days after infection, the gene expression of ISG15, CXCL-10, and OASL2 was significantly induced by virus (Online Resource 1D)." (PMID 39821815, 2025). "PBEC were able to be infected with IAV and infection caused an increase in expression of immune genes including CXCL10, IFNB1, ISG15 and SOCS1." (PMID 40496017, 2025). "Knockdown of STUB1 expression inhibited the inhibitory effect of Sec10 on the transcriptional levels of Isg15, Isg54, and Isg56 triggered by infection with VSV or HSV-1." (PMID 40920886, 2025). "Results showed that BTV infection produces a drastic decrease of Ifnα and Isg15 transcription levels induced by MVA infection and DNA transfection." (PMID 39836220, 2025). "Overall, our findings reveal a balancing act: ISG15 helps fight infection while also keeping inflammation in check, highlighting its dual role in immune defense and regulation." (PMID 40627782, 2025). "In these infections, ISG15 has been found to play a protective role by targeting viral proteins for ISGylation, leading to their degradation or functional impairment." (PMID 40284971, 2025). "Since secreted ISG15 has been shown to have immunoregulatory functions, we continued our study in mice with the aim to investigate the role of ISG15 in a fully immunocompetent infection model." (PMID 40627782, 2025). "Infection with WT-R VACV resulted in low levels of ISG15 and IFN-β transcripts in both cell lines, with on average a 0.5 to 3-fold increase in either transcript detected in the presence of RIG-I compared to in the ΔRIG-I cells." (PMID 40258008, 2025). "Among these proteins, in particular, TLR3 activated MSCs secreted TNFSF10, CXCL10, ISG15 and C2 (green highlight, 7C) were found upstream of several affected immune response and infection pathways in all 3 cell types." (PMID 40861855, 2025). "As part of the innate immune system, ISG15 is strongly induced by type I IFNs, and its conjugation to intracellular proteins and viral proteins (ISGylation) allows cells to fight off infection." (PMID 40631552, 2025). "Further analysis revealed that LSDV-dd001/156 infection also enhanced the expression of downstream ISGs, including ISG15 and ISG56, particularly in response to SeV stimulation." (PMID 40700455, 2025). "To validate this up-regulation, we quantified the expression of IL6, GBP1, GBP2 and ISG15 in the same infection condition as bulk RNA-seq by qPCR." (PMID 39777915, 2025).
infection (continued). "Further analysis was performed to determine the mRNA levels of IFN-β and ISG15 at different time points post-infection (hpi)." (PMID 41070967, 2025). "These analyses support the assumption that the immunomodulatory effects of ISG15 that we observed in vitro, were also active during infection in vivo." (PMID 40627782, 2025). "Two ISG15 genes are strongly upregulated 48 h post-infection (p.i.)while other ubiquitin genes were unaffected." (PMID 40630959, 2025). "ISG15−/− mice exhibited exacerbated inflammatory pathology and low levels of IL-10 in the FGT at the later stage of infection, suggesting that ISG15-induced IL-10 limits pathology during infection." (PMID 40627782, 2025). "This is supported by the observed defect of ISG15−/− mice to clear infection as efficiently as WT mice." (PMID 40627782, 2025). "In this study, despite significant production of IFNs in the lung during the infection, ISG15, ISG12(A), MX1, and MX2 genes were downregulated at 14 dpi, suggesting that PRRSV employs strategies to inhibit ISGs and facilitate in vivo replication." (PMID 40459260, 2025). "Upon MVA infection, the loss of STING hampered the expression of type I interferons (IFNs) and, in turn, interferon-stimulated gene 15 (ISG15) and interferon-induced transmembrane protein 3 (IFITM3)." (PMID 40981440, 2025). "ISG15 acts synergistically with IL-18 cytokine to increase the IFN-γ production by NK cells early after infection, which is critical for the rapid establishment of innate IFN-γ immunity and efficient clearance of the bacterial pathogen." (PMID 40627782, 2025). "This indicates that the secretion of ISG15 in response to Ct infection by WT organoids enhances the release of IFN-γ by NK cells in the co-culture system." (PMID 40627782, 2025). "To investigate the role of ISG15 in Ct infection in vivo, we performed mouse infection experiments in WT and ISG15−/− mice." (PMID 40627782, 2025). "On day two after infection, only gene expression of ISG15 was significantly induced by the virus (Online Resource 1A)." (PMID 39821815, 2025). "In response to VACV ΔE3L infection, we observed that cells expressing hDUSP11 (D11) had on average a 2-fold reduction in ISG15 mRNA levels and 3.6-fold reduction in IFN-β mRNA levels compared to the EV expressing cell line." (PMID 40258008, 2025). "ISG15 had a more modest impact on infection, which is consistent from the complex role of the protein." (PMID 41472248, 2025). "This mini-review summarizes the existing studies aimed at understanding the mechanisms behind the secretion and functions of extracellular ISG15, with a particular focus on its immunomodulatory effects during infection." (PMID 40719862, 2025). "To address the innate immune response after infection, we next evaluated ISG15 host gene expression by RT-qPCR." (PMID 39314478, 2024). "ISG15 is induced early during infection and has been shown to have a viral restriction role in several infection models." (PMID 38384473, 2024). "ISG15 expression in lungs was significantly lower in all cohorts compared to the vehicle-only cohort and is supportive of decreased infection in mice intranasally treated with ESE." (PMID 39772226, 2024). "Comparison with IFNα and IFNb, well-established inducers of ISG15 transcription, showed that, although robust, ISG15 levels upon infection were lower than upon exposure to 10 ng/mL IFNα/b." (PMID 39345209, 2024). "We found that ASFV-WT infection strongly suppressed the mRNA levels of Isg56, Isg15, Mx1, and Oas2 induced by IFN-α." (PMID 38620034, 2024). "We concluded from these observations that ISG15 synthesis by epithelial cell is increased upon infection by C. trachomatis." (PMID 39345209, 2024). "ISG15 is one of the most upregulated genes upon type I interferons treatment or infection by a wide range of viruses." (PMID 38776321, 2024).
infection (continued). "Neutrophils, which were identified in the brain at only small relative abundance, dramatically expanded in the blood after infection and upregulated antiviral response genes, including Ddx58, Ifih1, Ifit1, Ifit2 and Isg15." (PMID 39749347, 2024). "Quantification of cytokines and chemokines by ELISA confirmed that ISG15 broadly repressed the immune response to infection." (PMID 39345209, 2024). "Infection induced ISG15 expression, but to a lower extent than IFN-I did, and protein ISGylation was below detection limit." (PMID 39345209, 2024). "We uncovered the signaling cascade that led to an increase in ISG15 transcription and studied its outcome on infection." (PMID 39345209, 2024). "Subunit 1 of the eIF3 is one of the proteins interacting with ISG15 to regulate defense responses against infection." (PMID 38711504, 2024). "ISG15 gene is critical in host antiviral response with diverse and pathogen-dependent mechanisms to protect the host during infection by conjugating to a wide range of viral and cellular proteins." (PMID 38932231, 2024). "Specifically, it is possible that ISG15 directly regulates proteins exploited by viruses during early intracellular infection events." (PMID 38384473, 2024). "We showed that, following infection, ISG15 expression was initially high 3 days after symptom onset then decreased through day 28 of symptoms." (PMID 38580667, 2024). "Infection of HeLa cells and primary ecto-cervical epithelial cells resulted in a transcriptional upregulation of ISG15 expression." (PMID 39345209, 2024). "ISG15 and related enzymes are expressed at elevatedlevels whenan infection is present or when stimulated by IFNs." (PMID 39346869, 2024). "The fact that several ISGs, such as Isg15, Igs56, and Mx1 are highly upregulated during infection suggests that infected cells release sufficient IFNβ to induce the expression of genes associated with antiviral defense mechanisms." (PMID 36851549, 2023). "Third, these analyses uncovered a new EBV-imprinted subpopulation-ISG-15+CD8+ T cells that delineate an important step in infection-induced anti-tumour immunity." (PMID 37735150, 2023). "CVA6 infection leads to the increased expression of ISGs, including Oas2, Irf7, Ddx60, Ifit3, Ddx58, and Isg15, which exhibit immunopathogenic potential and are implicated in neural inflammation." (PMID 36851724, 2023). "The results show that both monomeric ISG15 and ISGylated proteins were detected during IHD-J-ISG15 infection." (PMID 37036376, 2023). "Among their related proteins, ISG15 plays a crucial role during infection across a wide range of viruses." (PMID 37632007, 2023). "The most highly induced gene was ISG15 at 2 and 4 days post-infection, while IFNa4 was highly induced at day 6 post-infection." (PMID 37651466, 2023). "The correct expression of the ISG15 protein was also confirmed by the presence of ISGylation after MVA-Δ3-ISG15GG infection (noted by smear of ISGylated protein) and its absence after infection with the mutated MVA-Δ3-ISG15AA." (PMID 37313341, 2023). "Samples with a parallel infection in the B. subtilis treatment group were analyzed by western blot, to confirm the results and determine the ISG15 ubiquitination level after treatment with B. subtilis." (PMID 37256060, 2023). "Our findings showed that vitamin D supplementation prior MHV-3 infection enhanced the expression of IFN-β and the interferon-stimulated genes Isg15 and Isg20 in the lungs upon infection." (PMID 38140675, 2023). "Overexpressing circMIB2 significantly boosted ISG15 protein levels while knocking it down inhibited ISG15 protein expression during SCRV infection." (PMID 37652905, 2023). "The mRNA expression levels of IL-6, IL-18, IFN-α, IFN-β, and ISG-15 were up-regulated during EV-G/YN23/2022 infection, while IL-1β, TNF-α, IFN-λ3, and IRF-7 maintained in relatively constant levels, and no cytokines were significantly reduced." (PMID 37632087, 2023).